MALAT1 (metastasis associated lung adenocarcinoma transcript 1)
Diseases named in the same sentence as MALAT1 in open-access papers (continued):
Sharing a sentence is not in itself a finding about the gene and the disease.
melanoma (57 papers, 2013 to 2025). A malignant, usually aggressive tumor composed of atypical, neoplastic melanocytes. "In melanoma, metastasis-associated lung adenocarcinoma transcript 1 (MALAT1) serves as an illustrative example: it sponges miR-22 and contributes to sustained mitogen-activated protein kinase (MAPK)-pathway signalling." (PMID 41463281, 2025). "In summary, the presented data provide new insights into the regulatory function of MALAT1 on MAPK-pathway associated gene expression in melanoma and highlights that MALAT1 maintains essential oncogenic functions while simultaneously being downregulated." (PMID 37235843, 2023). "Our results showed that MALAT1-ASO treatment decreased BRAF RNA expression and protein levels, and MALAT1 had increased correlation with MAPK-pathway associated genes in melanoma patient samples compared to healthy skin." (PMID 37235843, 2023). "This patient sample analysis is also in accordance with our finding that drug-induced MAPK-inhibition causes dose-dependent MALAT1-upregulation in NRAS-mutant melanoma." (PMID 37235843, 2023). "LncRNA MALAT1 (metastasis associated lung adenocarcinoma transcript 1) acts as a competing endogenous RNA (ceRNA) by sponging miR-22 to promote melanoma growth and metastasis." (PMID 31947678, 2020). "Pearson’s correlation analyses revealed that miR-34a expression was inversely associated with MALAT1 in melanoma tissues (r2 = 0.689, P = 0.0015)." (PMID 31101802, 2019). "In summary, we demonstrated that miR-34a expression is inversely associated with MALAT1 in melanoma tissues." (PMID 31101802, 2019). "Notably, the effectiveness of MALAT1-ASO treatment in inhibiting the survival and proliferation of NRAS- and BRAF-mutated melanoma cells is surprising in light of MALAT1 being strongly downregulated in patient samples of melanoma." (PMID 37235843, 2023). "Another possibility is that there may be other factors, such as other non-coding RNAs or signaling pathways, that regulate NRAS expression and compensate for the loss of MALAT1 in melanoma cell lines." (PMID 37235843, 2023). "Additionally, we used a large panel of patient-derived melanoma and healthy skin tissue to present gene expression correlation of MALAT1 and genes associated with MAPK signaling." (PMID 37235843, 2023). "However, using a large panel of NRAS- and BRAF-mutated cell lines as a model for MAPK-dependent melanoma, we show that MALAT1 expression is essential for melanoma colony formation, cell growth, and tumor growth." (PMID 37235843, 2023). "Furthermore, it was found that MALAT1 knockdown was followed by a decrease in melanoma cell migration, whereas HOTAIR knockdown was associated with suppression of cell motility and invasive potential, confirming the clinical utility of the studied lncRNAs." (PMID 35626352, 2022). "HOTAIR expression was found to be significantly higher in lymph node metastases compared to primary melanoma, whereas several other lncRNAs, including MALAT1, Urothelial carcinoma-associated 1 (UCA1), and nuclear-enriched transcript 1 (NEAT1), showed no change in their expression patterns." (PMID 28350340, 2017). "Broadly viewed, our literature analysis revealed that HOTAIR, H19, and MALAT1 are the main oncogenic lncRNAs studied, and correlated to the aggressiveness of melanoma phenotype and in the acquisition of drug resistance." (PMID 40282449, 2025). "Fifty nontargeting sgRNAs were incorporated as negative controls as well as positive controls against five known melanoma-associated lncRNAs (BANCR, CDKN2B-AS1, HOTAIR, MALAT1, and SAMMSON)." (PMID 40552742, 2025). "Among the best-characterised pro-angiogenic lncRNAs in melanoma are MALAT1, HOTAIR, BANCR, SLNCR1, and DANCR." (PMID 41463281, 2025). "It has been previously demonstrated that MALAT1 is able to reduce miR-34a action in melanoma cells by acting as a “sponge” via its direct binding to miR-34a." (PMID 40863726, 2025).
melanoma (continued). "The analysis of the literature showed that HOTAIR, MALAT1, and H19 are the oncogenic lncRNAs most studied in melanoma, while MEG3 is an important tumor suppressor decreased in this cancer." (PMID 40282449, 2025). "Knockdown of endogenous miR-34a-5p in A375 melanoma cells resulted in an increase in MALAT1 levels, further confirming the regulatory relationship." (PMID 40863726, 2025). "MALAT1 also triggered malignant melanoma growth and metastasis by sponging miR-22, consequently upregulating the miR-22 targets MMP14 and Snail." (PMID 38561330, 2024). "There have been several promising preclinical studies using ASOs and siRNAs to target MALAT1 in various human tumors, including melanoma." (PMID 37235843, 2023). "Previously presented cancer-specific MALAT1-upregulation in melanoma was executed by comparing biopsies of close distance derived from the same patients (paired samples)." (PMID 37235843, 2023). "Our findings indicate that MALAT1 inhibition strongly reduces colony growth abilities of individual melanoma cells." (PMID 37235843, 2023). "MALAT1-ASO treatment strongly impaired cell growth and colony formation in a large panel of NRAS- and BRAF-mutated melanoma cells, including MEKi-resistant cells." (PMID 37235843, 2023). "(ρ = 0.524) In a next step we analyzed the TCGA (melanoma) and GTEx (healthy skin) databases for potential alterations of gene expression of MALAT1 in relation to NRAS, BRAF, MEK1, MEK2, ERK1 and ERK2 gene expression." (PMID 37235843, 2023). "We then aimed to identify the role of MALAT1 in the clonogenic potential of NRAS-mutant melanoma cells using a colony formation assay in the D04 cell line." (PMID 37235843, 2023). "We also observed a decrease in BRAF RNA levels and protein expression upon MALAT1 inhibition in melanoma." (PMID 37235843, 2023). "We demonstrate the impacts of antisense oligonucleotide (ASO)-based MALAT1-inhibition on MAPK-pathway gene regulation in melanoma." (PMID 37235843, 2023). "MAPK-pathway upregulation is the main event in the development and progression of human cancer, including melanoma and recent studies have shown that MALAT1 has a significant impact on the regulation of gene and protein expression in the MAPK pathway." (PMID 37235843, 2023). "MALAT1 also serves as a negative regulator of miR034a, which, in turn, regulates the expression of c-myc in melanoma cells, a well-known oncogene that is constitutively expressed in a multitude of malignant cancer types." (PMID 37373059, 2023). "MALAT1 seems to be downregulated in melanoma, while simultaneously exercising essential oncogenic functions." (PMID 37235843, 2023). "Our aim was to study the regulatory functions of MALAT1 on gene expression of MAPK-pathway key kinases in melanoma." (PMID 37235843, 2023). "In this study, we present novel transcriptional dependencies between MALAT1 and MAPK-pathway-associated genes in melanoma." (PMID 37235843, 2023). "This interactive cross-talk reveals MALAT1 as a critical cell cycle regulator in melanoma cells, and its overexpression has been correlated with the progression of melanoma cell growth." (PMID 37373059, 2023). "As already seen in the normalized data, MALAT1 expression was significantly decreased in BRAF- and NRAS-mutated melanoma (13.5-fold, p < 0.001), LIHC (3.3-fold, p < 0.001) and LUSC (8.7-fold, p < 0.001), when compared to their corresponding healthy tissue." (PMID 37235843, 2023). "We tested MALAT1-ASO treatment on four trametinib-resistant melanoma cell lines: D04RM, MM415RM, WM3629-RM and Sk-Mel-2RM." (PMID 37235843, 2023). "Similar results of MALAT1 upregulation and promotion of tumor cell proliferation, migration, and invasiveness were detected in melanoma and in endometrial carcinoma." (PMID 35096427, 2022). "The levels of UCA1 and MALAT-1 were remarkably more elevated in patients with melanoma compared to healthy controls, and their levels were associated with the stage of the disease." (PMID 36614156, 2022).
melanoma (continued). "For instance, SNHG16, TTN-AS1, and MALAT1 are overexpressed in melanoma and exert oncogenic effects." (PMID 33674778, 2022). "For example, knocking down MALAT1 in melanoma cells significantly upregulated the expression of tumor-suppressing MiR34a." (PMID 33477898, 2021). "For example, the recently characterized metastasis-associated-in-lung-adenocarcinoma transcript-1 (MALAT1), a well-conserved lncRNA that is implicated in diseases in humans, was shown to bind MiR34a in melanoma cells, thereby lowering MiR34a levels." (PMID 33477898, 2021). "Meanwhile, they demonstrated that the migration ability of melanoma cells was suppressed by silencing LncRNA MALAT1 in vitro." (PMID 33875645, 2021). "To broaden our results, we analyzed the effect of MALAT1 inactivation in A2058 melanoma cell line which also exhibits a prevalent amoeboid morphology in 3D collagen." (PMID 32369931, 2020). "MALAT1 knockdown was followed by a decrease in melanoma cell migration, whereas colony formation and metastatic ability of cancer cells were diminished in the absence of ANRIL." (PMID 33203119, 2020). "Another more recent study revealed that MALAT1 promotes melanoma development by downregulating miR-23a." (PMID 33392203, 2020). "This study presents strong evidence that MALAT1 is overexpressed in melanoma tissues and functions as a molecular sponge that competitively inhibits miR-34a and modulates the abundance of the targeted c-Myc and Met." (PMID 31101802, 2019). "We demonstrated that miR-34a is negatively correlated with MALAT1 in melanoma cells and tumor specimens." (PMID 31101802, 2019). "The expression level of MALAT1 is closely related to melanoma progression, as, for instance, silence of MALAT1 would delay tumour growth of melanoma, indicating the potential of MALAT1 as a theranostic target of melanoma treatment 27,28." (PMID 31413743, 2019). "In this study, we investigated the MALAT1 and miR-34a levels in melanoma, and explored the correlation between MALAT1 and miR-34a production." (PMID 31101802, 2019). "MALAT‐1 was demonstrated to increase progressively in melanoma progression in a cohort of 63 primary melanomas, adjacent normal tissue and metastatic lesions." (PMID 30499222, 2019). "The qRT-PCR results showed that MALAT1 was more highly expressed in the melanoma tissues than in the benign nevi." (PMID 31101802, 2019). "In this study, we revealed that MALAT1 is more highly expressed in melanoma tissues than in benign nevi, and it contains functional sequence-specific miR-34a-binding sites." (PMID 31101802, 2019). "The results of the RNAscope assay were consistent with those of the qRT-PCR, with significantly higher MALAT1 levels in melanoma tissues than in benign nevi." (PMID 31101802, 2019). "To investigate the potential mechanisms regulating the effects of MALAT1 on melanoma cells, we analyzed a miRNA-seq transcriptome of A375 melanoma cells transfected with MALAT1 siRNA or a scrambled control." (PMID 31101802, 2019). "A recent studies have elucidated that MALAT1 down-regulated the expression of tumor-suppressor miR-22 by means of sponging, thus promoted melanoma development." (PMID 27966454, 2017). "In general, our study suggested that miR-183 suppressed cell growth by inhibiting ITGB1 signal pathway and MALAT1 promoted melanoma growth by acting as a ceRNA of miR-183 in melanoma." (PMID 27966454, 2017). "An increasing number of studies have found the ceRNA activity of lncRNA MALAT1, especially in melanoma." (PMID 27966454, 2017). "Collectively, these data indicated that MALAT1 promoted melanoma growth by regulating miR-183 expression." (PMID 27966454, 2017). "The expression of MALAT1 in 63 lymph node metastatic tissue samples was higher than in paired primary melanomas." (PMID 28415644, 2017). "MALAT1 knockdown resulted in impaired melanoma migration, implying possible effects on tumor dissemination." (PMID 28350340, 2017).
melanoma (continued). "Patient-derived melanoma samples demonstrated a significantly higher MALAT1 expression in lymph node metastases, compared to the primary tumor and to adjacent tissue." (PMID 28350340, 2017). "In brief, our results revealed a novel regulatory mechanism that was comprised of the MALAT1-miR-183-ITGB1 axis in melanoma." (PMID 27966454, 2017). "In this study, we report that MALAT1 is up-regulated in melanoma and promotes melanoma cell proliferation, invasion and migration." (PMID 27564100, 2016). "We initially investigated MALAT1 expression in twenty pairs of primary malignant melanoma tissues and adjacent normal tissues by real-time PCR." (PMID 27564100, 2016). "MALAT1 can promote the growth and metastasis of melanoma cells though sponging miR-22, functionally releasing MMP14 and Snail mRNA transcripts targeted by miR-22, causing MMP2 activation and E-cadherin down-regulation, and inducing ECM remodelling and EMT." (PMID 27564100, 2016). "And lastly, we found that MALAT1 promoted melanoma cell growth and metastasis by competitively binding the miR-22, up-regulating MMP14 and Snail, and having downstream effects on MMP2 and E-cadherin protein." (PMID 27564100, 2016). "We also demonstrated that MALAT1 promoted the proliferation, invasion and migration of melanoma cells by acting as a competing endogenous RNA (ceRNA) for miR-22." (PMID 27564100, 2016). "The CCK8 assay revealed that decreased MALAT1 significantly inhibited the proliferative ability of melanoma cells." (PMID 27564100, 2016). "Subsequently, we demonstrated that MMP14 and Snail were the downstream target of MALAT1 ceRNA function and were important for MALAT1 to regulate melanoma cell phenotypes, suggesting that MALAT1 affected melanoma progression in a miR-22 site-dependent manner." (PMID 27564100, 2016). "We determined that MALAT1 promotes melanoma cells proliferation, invasion and migration by sponging miR-22." (PMID 27564100, 2016). "MALAT1 acts as a ceRNA for miR-22, a tumour suppressor in melanoma." (PMID 41463281, 2025). "As a result, MALAT1 stimulates the invasion and migration of melanoma cells." (PMID 41463281, 2025). "Finally, regarding the regulation of MMPs, the literature indicates that the well-known oncogenic lncRNA, MALAT1, is upregulated in melanoma where, by sponging the miR-22, increases the expression of MMP14 and SNAIL." (PMID 40282449, 2025). "For example, lncRNA MALAT1 could bind to miR-23a, promoting proliferation, migration, and invasion of melanoma." (PMID 38561355, 2024). "Moreover, MALAT1 expression also was significantly decreased in melanoma compared to healthy skin when put in relationship to gene expression of the MAPK pathway genes NRAS, BRAF, MEK1, MEK2, ERK1, and ERK2." (PMID 37235843, 2023). "Contrary to our expectations, MALAT1 expression was found to be strongly decreased in melanoma." (PMID 37235843, 2023). "Our next step was to explore whether melanoma cells with acquired trametinib-resistance keep their vulnerability to MALAT1-ASO treatment." (PMID 37235843, 2023). "To determine if stable MALAT1 RNA levels are a common requirement in melanoma, we applied MALAT1-ASO treatment to a group of NRAS- and BRAF-mutant melanoma cell lines in vitro, including primary derived cell lines and cell lines with acquired resistance to the MEKi trametinib." (PMID 37235843, 2023). "Furthermore, we showed that MALAT1-ASO treatment significantly impaired tumor growth in vivo in a xenograft NRAS-mutant melanoma mouse model." (PMID 37235843, 2023). "Additionally, we show that healthy human melanocytes were not vulnerable to MALAT1-ASO treatment, indicating that cell growth inhibition due to MALAT1 degradation is a specific vulnerability of melanoma cells." (PMID 37235843, 2023). "Additionally, MALAT1 has been found to serve as a negative regulator of miR-183 in melanoma cells, thereby controlling the output expression of ITGB1 (integrin subunit beta 1)." (PMID 37373059, 2023).
melanoma (continued). "Most of the correlations were stronger in melanoma when compared to healthy skin, indicating that MALAT1 may play a role in the dysregulation of MAPK signaling in melanoma." (PMID 37235843, 2023). "In addition to showing that ASO-mediated MALAT1 degradation significantly inhibits melanoma cell survival, we also observed strong downregulation of MALAT1 in melanoma when compared to healthy skin." (PMID 37235843, 2023). "MALAT1 promotes the growth and migration of melanoma cells by interacting with miRNAs." (PMID 36032150, 2022). "According to our findings, MALAT1 might also be a crucial factor in the tumorigenesis and development of melanoma." (PMID 32993558, 2020). "Furthermore, MALAT1 downregulates miR-34a expression level in melanoma cells and tumor specimens, thereby it is a potential biomarker for many human cancer diagnosis as well as prognosis." (PMID 33392203, 2020). "Interestingly, MALAT1, which contains functional sequence-specific miR-34a-binding sites, regulates miR-34a stability in melanoma cells and in vivo." (PMID 31101802, 2019). "Moreover, MALAT1 functions as a molecular sponge for miR-34a, and helps regulate the expression of c-Myc and Met in melanoma cells." (PMID 31101802, 2019). "Future investigations of the crosstalk between MALAT1 and miR-34a may provide useful insights for developing new strategies to improve the efficacy of melanoma treatments." (PMID 31101802, 2019). "To explore whether MALAT1 regulates miR-34a in clinical tissue samples, we analyzed miR-34a expression and assessed its correlation with MALAT1 in 20 melanoma tissues and 20 nevi." (PMID 31101802, 2019). "Thus, our findings provided a better understanding of the non-coding RNA interaction regulatory network by MALAT1-miR-183-ITGB1 axis in the development of melanoma." (PMID 27966454, 2017). "Melanoma cells with high levels of MALAT1 showed an increase in ITGB1 expression, which could be markedly inversed by transfection with miR-183." (PMID 27966454, 2017). "MALAT1 promotes melanoma growth and metastasis via sponging miR-22." (PMID 28935763, 2017). "Collectively, we found a new signaling pathway promoting melanoma development by MALAT1-miR-183-ITGB1 axis, which may be clinically valuable as new targets for malignant melanoma therapy." (PMID 27966454, 2017). "We further investigated whether MMP14 and Snail expression could be influenced by MALAT1 in melanoma cells." (PMID 27564100, 2016). "Understanding the regulatory mechanism of MALAT1 in melanoma could lead to the identification of novel therapeutic targets for melanoma." (PMID 27564100, 2016). "Furthermore, high expression of MALAT1 was found exclusively in metastatic tissues developed in lymph node, and knockout of MALAT1 inhibits melanoma cell migration in vitro." (PMID 27686732, 2016). "The effects of MALAT1 in malignant melanoma is verified using a xenograft model." (PMID 27564100, 2016). "Metastasis-associated lung adenocarcinoma transcript 1 (MALAT1), an lncRNAs, is associated with the growth and metastasis of many human tumors, but its biological roles in malignant melanoma remain unclear." (PMID 27564100, 2016). "In this study, we showed that the expression of MALAT1 was increased in melanoma patients." (PMID 27564100, 2016). "MALAT1 was markedly increased in melanoma tissues compared to adjacent normal tissues." (PMID 27564100, 2016). "Some researchers have discovered that MALAT1 is highly expressed in melanoma and may have a correlation with melanoma metastasis." (PMID 27564100, 2016). "MALAT1 promoted melanoma cell growth and metastasis by operating as a ceRNA for the miR-22." (PMID 27564100, 2016). "Moreover, the effect of MALAT1 on the migration and invasion of melanoma cells was also largely abrogated by an miR-22 mimic." (PMID 27564100, 2016). "We subsequently demonstrated that MALAT1 is negatively regulated by miR-22 and that MALAT1 could act as a ceRNA by sponging miR-22 in melanoma cells." (PMID 27564100, 2016).